GNG10 (G protein subunit gamma 10)
Description:
Guanine nucleotide-binding proteins (G proteins) are involved as a modulator or transducer in various transmembrane signaling systems. The beta and gamma chains are required for the GTPase activity, for replacement of GDP by GTP, and for G protein-effector interaction. Interacts with beta-1 and beta-2, but not with beta-3.
Tractability: Antibody: UniProt places it where antibodies can reach, with high confidence; its Gene Ontology location is reachable by antibodies, with high confidence.
Gene: Protein-coding gene on chromosome 9 (111,661,561 to 111,670,473, forward strand). Ensembl gene ENSG00000242616.
Subcellular location: Cell membrane
Pathways (Reactome):
Signal Transduction: Ca2+ pathway; Extra-nuclear estrogen signaling; G alpha (12/13) signalling events; G alpha (i) signalling events; G alpha (q) signalling events; G alpha (s) signalling events; G alpha (z) signalling events; G beta:gamma signalling through BTK; G beta:gamma signalling through CDC42; G beta:gamma signalling through PI3Kgamma; G beta:gamma signalling through PLC beta; G-protein activation; GPER1 signaling; Glucagon-type ligand receptors
Hemostasis: ADP signalling through P2Y purinoceptor 1; ADP signalling through P2Y purinoceptor 12; Prostacyclin signalling through prostacyclin receptor; Thrombin signalling through proteinase activated receptors (PARs); Thromboxane signalling through TP receptor
Metabolism: Adrenaline,noradrenaline inhibits insulin secretion; Glucagon signaling in metabolic regulation; Glucagon-like Peptide-1 (GLP1) regulates insulin secretion
Neuronal System: Activation of G protein gated Potassium channels; Inhibition of voltage gated Ca2+ channels via Gbeta/gamma subunits; Presynaptic function of Kainate receptors
Cellular responses to stimuli: High laminar flow shear stress activates signaling by PIEZO1 and PECAM1:CDH5:KDR in endothelial cells
Disease: ADORA2B mediated anti-inflammatory cytokines production
Metabolism of proteins: Cooperation of PDCL (PhLP1) and TRiC/CCT in G-protein beta folding
Transport of small molecules: Vasopressin regulates renal water homeostasis via Aquaporins
Gene Ontology:
Molecular function: protein binding; G-protein beta-subunit binding; GTPase activity
Biological process: G protein-coupled receptor signaling pathway; signal transduction
Cellular component: heterotrimeric G-protein complex; plasma membrane
Genetic constraint (gnomAD): Loss-of-function variants: 6 observed, 3.83 expected, observed/expected ratio (o/e) 1.57, 90% interval 0.77 to 1.94. That is too few expected variants to judge how well the gene tolerates losing a copy. Missense variants: 44 observed, 57.4 expected, observed/expected ratio (o/e) 0.77, 90% interval 0.6 to 0.99. Synonymous variants: 16 observed, 20.25 expected, observed/expected ratio (o/e) 0.79, 90% interval 0.53 to 1.2.
Homologues: Orthologues: chimpanzee GNG10 (100% identical), dog GNG10 (96% identical), mouse Gng10 (96% identical), pig GNG10 (94% identical), tropical clawed frog gng10 (85% identical), rat Gng10-ps1 (84% identical), zebrafish gng10 (76% identical), Drosophila melanogaster Ggamma1 (32% identical). Paralogues in human: GNG5 (53% identical), GNG3 (51% identical), GNG5B (51% identical), GNG2 (50% identical), GNG7 (50% identical), GNG4 (47% identical), GNG8 (47% identical), GNG12 (46% identical), GNGT2 (35% identical), GNGT1 (31% identical), GNG11 (29% identical).
Diseases named in the same sentence as GNG10 in open-access papers:
GNG10 is named in the same sentence as 11 diseases in open-access papers, as found by Europe PMC text mining. Sharing a sentence is not in itself a finding about the gene and the disease. The quoted sentences say what the papers report.
colorectal cancer (5 papers, 2021 to 2026). A primary or metastatic malignant neoplasm that affects the colon or rectum. "Guanine nucleotide-binding protein gamma 10 (GNG10) is implicated in various biological processes, yet its specific oncogenic role in colorectal cancer (CRC) remains poorly defined." (PMID 42252561, 2026). "Overexpression of GNG10 promotes colorectal cancer progression, and we found that GNG10 expression was higher in the RET Null, suggesting an association between GNG10 and HSCR." (PMID 37144136, 2023). "In summary, our findings revealed that lncRNA CCAT1 facilitated colorectal cancer progression via the hsa-miR-4679/GNG10 axis and provided new potential therapeutic targets for colorectal cancer." (PMID 35005034, 2021). "The data suggested that knockdown of lncRNA CCAT1 inhibits the progression of colorectal cancer via hsa-miR-4679 mediating the expression of GNG10." (PMID 35005034, 2021). "We have identified a new CCAT1/hsa-miR-4679/GNG10 axis involved in the development of colorectal cancer." (PMID 35005034, 2021). "Studies have shown that overexpression of Gng10 promotes the progression of colorectal cancer." (PMID 36185082, 2022). "GNG10 overexpression promoted the progression of colorectal cancer, and this phenotype could be reversed by miR-4679 mimics." (PMID 35005034, 2021).
melanoma (3 papers, 2014 to 2023). A malignant, usually aggressive tumor composed of atypical, neoplastic melanocytes. "In 2010, GNG10 mutations were found in melanoma, indicating the mutated hetero-trimetric G proteins were involved in melanoma progression." (PMID 35005034, 2021). "GNG10 encodes G protein subunit γ 10 and is mutated in melanoma." (PMID 24498386, 2014).
head and neck squamous cell carcinoma (2 papers, 2021 to 2022). A squamous cell carcinoma that arises from any of the following anatomic sites: lip and oral cavity, nasal cavity, paranasal sinuses, pharynx, larynx, and salivary glands. "Recently, a study reported that GNG10 was dysregulated and associated with survival of head and neck squamous cell carcinoma (HNSCC) patients." (PMID 35005034, 2021). "A study on the peripheral blood mononuclear cells based on peripheral blood RNA-Seq indicated the GNG10 imbalance in the head and neck squamous cell carcinoma, which is related to the survival rate of patients." (PMID 35938142, 2022).
COVID-19 (1 paper, 2024). A disease caused by infection with severe acute respiratory syndrome coronavirus 2. "The identification of MYBL2, RBM6, VEPH1, AHNAK2, GNG10, and DUSP14 as key genes offers valuable insights into the molecular mechanisms underpinning glioma progression and its interaction with COVID-19." (PMID 39684661, 2024).
glioma (1 paper, 2024). A benign or malignant brain and spinal cord tumor that arises from glial cells (astrocytes, oligodendrocytes, ependymal cells). "MYBL2, GNG10, and AHNAK2 exhibited an elevated gene expression in recurrent gliomas, suggesting involvement in cancer progression (e.g., MYBL2 p = 5.5 × 10−6)." (PMID 39684661, 2024).
cancer (4 papers, 2021 to 2026). A tumor composed of atypical neoplastic, often pleomorphic cells that invade other tissues. "Both pharmacological inhibition with Box5 and genetic ablation of RHOA effectively abrogated GNG10-induced oncogenic phenotypes and the upregulation of cancer stem cell markers (CD44, CD133, OCT4, Nanog, SOX2)." (PMID 42252561, 2026).
tumor (2 papers, 2021 to 2026). "Multivariate analysis indicated that the prognostic value of GNG10 is closely associated with tumour progression." (PMID 42252561, 2026). "In vivo xenograft models confirmed that GNG10 knockdown suppressed tumour growth and decreased the expression of proliferation and stemness markers." (PMID 42252561, 2026). "The results showed that GNG10 overexpression significantly promoted tumor growth." (PMID 35005034, 2021).
GNG10 also shares sentences with these, for which no sentence is quoted: Cerebral ischemia (1 paper); cognitive decline (1); mild cognitive impairment (1); Parkinson disease (1).